TSLP (thymic stromal lymphopoietin)
Diseases named in the same sentence as TSLP in open-access papers (continued):
Sharing a sentence is not in itself a finding about the gene and the disease.
colon cancer (continued). "We here demonstrate that TSLP was down-regulated in human colon tumors, which negatively correlates with the advanced stage of this disease." (PMID 26919238, 2016). "This was further supported by our findings that TSLP significantly promoted the apoptosis of all three colon cancer cell lines." (PMID 26919238, 2016). "Taken together, these results demonstrate that TSLP is able to inhibit tumor growth in a xenograft mouse model of colon cancer, which is dependent on TSLPR signaling in cancer cells." (PMID 26919238, 2016). "We next investigated the signaling pathway by which TSLP induced the apoptosis of colon cancer cell." (PMID 26919238, 2016). "The ability of TSLP to promote the apoptosis of colon cancer cells was further confirmed by using xenograft mouse model of colon cancer, underscoring the anti-tumor effect of TSLP." (PMID 26919238, 2016). "TSLPR, the receptor of TSLP, was expressed in all three colon cancer cell lines investigated and colon tumor tissues." (PMID 26919238, 2016). "We next investigated the biological effects of TSLP on colon cancer cells by adding exogenous TSLP to the cell culture of three colon cancer cell lines at increased concentrations for 48 h." (PMID 26919238, 2016). "More importantly, we found that the patients with tumoral TSLP expression at the lowest levels had the most advanced diseases, indicating a tumor-suppressing role of TSLP in colon cancer." (PMID 26919238, 2016). "The tumor tissues from patients with stage A colon cancer had significantly higher TSLP expression at both mRNA and protein levels than those from patients with stage B, C and D colon cancer." (PMID 26919238, 2016). "The addition of TSLP significantly enhanced apoptosis of colon cancer cells in a TSLPR-dependent manner." (PMID 26919238, 2016). "TSLP treatment significantly increased the percentage of apoptotic colon cancer cells that showed green fluorescence emitted by JC-monomers in a concentration-dependent manner." (PMID 26919238, 2016). "To assess TSLP expression levels in colon cancer, we first compared the gene expression of TSLP in colon adenomas with that in normal mucosa from the same individuals by using well-annotated NCBI GEO datasets." (PMID 26919238, 2016). "To confirm the apoptosis-promoting effect of TSLP on primary colon cancer cells, we FACS sorted EpCAM+ cells from tumor tissues from patients with colon cancer and treated them with TSLP (100 ng/ml) for 48 h." (PMID 26919238, 2016). "In a mouse model of colitis associated with CRC, TSLP mRNA was overexpressed in colon cancer compared to non-tumor sites and control mice." (PMID 40873585, 2025). "High concentrations of TSLP inhibited colon cancer growth in vitro." (PMID 40873585, 2025). "TSLP promoted apoptosis of colon cancer cells through the engagement of TSLPR." (PMID 40873585, 2025). "We then evaluated the effect of TSLP on the growth of colon cancer cells in vitro and in vivo." (PMID 26919238, 2016). "Moreover, administration of exogenous TSLP is able to promote the apoptosis of human colon cancer cells, and inhibit colon tumor growth in a xenograft mouse model of colon cancer in a TSLPR-dependent manner." (PMID 26919238, 2016). "We next investigated the effect of TSLP on tumor growth in the xenograft mouse colon cancer model." (PMID 26919238, 2016). "However, we still cannot exclude the possibility of TSLP directly acting on immune cells to regulate the growth of colon cancer." (PMID 26919238, 2016). "Moreover, we also confirmed the apoptosis-promoting effect of TSLP on primary colon cancer cells isolated from human colon tumors." (PMID 26919238, 2016). "Collectively, our study reveals a novel anti-tumor effect of TSLP via direct promotion of the apoptosis of colon cancer cells, and suggests that TSLP could be of value in treating colon cancer." (PMID 26919238, 2016).
colon cancer (continued). "Furthermore, we demonstrated that extrinsic apoptosis pathway was involved in apoptosis-promoting effect of TSLP, as cleaved caspase-8 was greatly increased in TSLP-treated colon cancer cells and caspase-8 inhibitor markedly decreased cancer cell apoptosis." (PMID 26919238, 2016). "We next examined whether TSLP influenced the apoptosis of colon cancer cells by Annexin V-PI double staining." (PMID 26919238, 2016). "In summary, our study reveals a novel anti-tumor function of TSLP by inducing the apoptosis of colon cancer cells in a TSLP-dependent way, and decreased TLSP levels could contribute to the growth of colon tumor." (PMID 26919238, 2016). "The lowest expression levels of TSLP were found in the tumor samples from patients with stage D colon cancer that usually predicts remote metastasis and poor prognosis, although TSLP expression levels were comparable between tumor tissues from stage B and stage C patients." (PMID 26919238, 2016). "Inhibition of caspase-8 almost completely reversed the apoptotic levels of SW1116, SW480 and DLD-1 cells after TSLP stimulation at 100 ng/ml to the baseline levels, and significantly decreased apoptosis of colon cancer cells after TSLP stimulation at 200 ng/ml." (PMID 26919238, 2016). "The preference of TSLP to promote the apoptosis of colon cancer cells could be due to aberrant signaling networks in cancer cells which may cause different signaling pathway mediated by TSLP." (PMID 26919238, 2016). "In addition, TSLP-mediated antitumor effects have also been reported in skin, colon cancer, and BC." (PMID 35558081, 2022). "Moreover, TSLP enhanced apoptosis of colon cancer cells through the engagement of TSLPR." (PMID 30057581, 2018). "Taken together, our data demonstrated that TSLP expression was down-regulated in the tumor tissue of patients with colon cancer, moreover, TSLP expression levels may negatively correlate with the severity of colon cancer." (PMID 26919238, 2016). "Thus, our study suggests TSLP could be a potential therapeutic target for colon cancer, particularly those with compromised immune system after long-term chemotherapy or radiotherapy." (PMID 26919238, 2016). "Interestingly, we found that TSLP positively correlated with miR-375 expression in colon tumors tissues, implying a possible involvement of miR-375 in down-regulated TSLP expression in colon cancer cells." (PMID 26919238, 2016). "mRNA expressions and protein levels of TSLP, TSLPR-α subunit, and IL-7R-α subunit showed a 4-fold increase in colon cancer tissues when compared to normal colon tissues." (PMID 34573368, 2021). "We found that TSLP activated MAPKs (JNK and p38) and STAT5, but, interestingly, down-regulated phosphorylation of STAT3 in colon cancer cells." (PMID 26919238, 2016). "To assess the role of TSLPR signaling in TSLP-induced cancer cell apoptosis, we knocked down TSLPR expression in all three colon cancer cell lines by small interfering RNA (siRNA)." (PMID 26919238, 2016). "In colon cancer, PGE2 can suppress the function of various immune cells such as macrophages, neutrophils, Th1, CTL, and NK cells, and on the other hand, augment the activity of cells such as TSLP-dependent Th2, Th17, and Treg48." (PMID 38008819, 2023). "Moreover, our in vivo results demonstrated that tumor-inhibitory effect of TSLP was, at least partly, mediated by TSLPR expressed in colon tumor cells." (PMID 26919238, 2016). "In this study, we examined the expression of TSLP at both mRNA and protein levels in colon tumor and macroscopically uninvolved surrounding tissues from surgical specimens, and TSLPR expression in human colon cancer cells and tumor tissues." (PMID 26919238, 2016). "Here we for the first time showed that colon cancer cells expressed TSLPR, suggesting that TSLP might directly act on colon cancer cells." (PMID 26919238, 2016).
colon cancer (continued). "Taken together, these results demonstrate that TSLP is able to promote the apoptosis of primary colon cancer cells, but not non-transformed colonic human epithelial cells." (PMID 26919238, 2016). "Taken together, these results demonstrate that human colon cancer cells and tumor tissues express the TSLPR and could respond to TSLP." (PMID 26919238, 2016). "Interestingly, TSLP selectively induced the apoptosis of colon cancer cells, but not normal colonic epithelial cells." (PMID 26919238, 2016). "However, Th2 cells are not a prognostic factor for colon cancer, suggesting that the role of TSLP in colon cancer could be independent of its effect on Th2 immunity." (PMID 26919238, 2016). "In addition, our results on lovo cells (colon cancer cells) shown that, TSLP is able to increase the expression of same cytokines inflammatory as Il-1, Il-4, Il-12 and IL-23 and in turn, these cytokines increase TSLP expression more than 4 times (results not shown)." (PMID 34573368, 2021).
rheumatoid arthritis (14 papers, 2012 to 2024). A chronic, systemic autoimmune disorder characterized by inflammation in the synovial membranes and articular surfaces. "Furthermore, TSLP has been linked to rheumatoid arthritis (RA): increased TSLP levels in synovial fluid of patients with RA in comparison to those with osteoarthritis have been reported in several studies." (PMID 32849527, 2020). "TNF‐α stimulation of synovial cells from rheumatoid arthritis patients induces expression of TSLP, and the blood concentration of TSLP in rheumatoid arthritis patients is elevated compared with the concentration in patients with an osteoarthritic knee." (PMID 32211586, 2020). "In multiple sclerosis and rheumatoid arthritis (RA), TSLP activates TH1/TH17 immune response." (PMID 36287299, 2022). "TSLP was reported to overexpressed in the skin samples of psoriasis, systemic sclerosis (SSc), and synovial fluid of rheumatoid arthritis (RA)." (PMID 36076269, 2022). "The aim of this study was to investigate PD-1/PD-L1 involvement in the hyporesponsiveness of rheumatoid arthritis (RA) synovial fluid (SF) CD4 T cells upon stimulation by thymic stromal lymphopoietin (TSLP)–primed CD1c myeloid dendritic cells (mDCs)." (PMID 25433812, 2014). "In rheumatoid arthritis (RA) patients, the expression levels of TSLP and IL-17 are increased in the synovial fluid." (PMID 23194010, 2012). "The cytokines interleukin (IL)-7 and thymic stromal lymphopoietin (TSLP) signal through the IL-7R subunit and play proinflammatory roles in experimental arthritis and rheumatoid arthritis (RA)." (PMID 26110994, 2015).
atopic asthma (13 papers, 2008 to 2025). An asthma that is characterized by symptoms that are triggered by an allergic reaction caused by inhaled allergens such as dust mite allergen, pet dander, pollen and mold. "Our study showed that both periostin and TSLP were associated with eosinophilic airway inflammation and seemed to be important drivers of atopic asthma pathobiology." (PMID 33203095, 2020). "It is well-established that TSLP is overexpressed in T2-driven atopic asthma and that a variety of environmental factors, including mechanical injury, toll-like receptor (TLR) ligands, viruses, and cytokines, can induce its production." (PMID 40370530, 2025). "Considering the categorization into groups, patients with atopic asthma exhibited lower concentrations of TSLP than those with non-atopic asthma." (PMID 38731070, 2024). "Antibodies AMG157 targeting TSLP are currently being evaluated for patients with mild atopic asthma in a Phase Ib clinical trial (ClinicalTrials.gov identifier: NCT01405963)." (PMID 24167583, 2013). "In this review, the signal transduction around human TSLP in the cascade of events in the development of atopic asthma is discussed." (PMID 18724870, 2008). "In atopic asthma, many different agents such as viruses, bacteria and allergens can induce a TSLP-dependent inflammatory response, leading to an inappropriate activation of both the innate and the adaptive immune system." (PMID 18724870, 2008). "Human TSLP is produced by different cell types in atopic asthma, mainly by epithelial and smooth muscle cells and induces an inflammatory Th2 response." (PMID 18724870, 2008). "Compelling evidence has been acumulated for a determinative role of TSLP in the initiation and maintenance of the allergic response in the context of atopic asthma." (PMID 18724870, 2008). "Also in 2011, a phase I clinical trial (NCT01405963) was initiated in adults with mild atopic asthma to investigate tezepelumab, a human monoclonal antibody with TSLP blocking properties." (PMID 41354649, 2025). "In atopic asthma, allergens release proteases, which disrupt the epithelial barrier and induce secretion of alarmins such as interleukin-25 (IL-25), interleukin-33 (IL-33), and thymic stromal lymphopoietin (TSLP) from epithelial cells." (PMID 38352244, 2023). "In a Phase I RCT the anti-TSLP mAb fragment ecleralimab (CSJ117) 4 mg was administered via a dry powder inhaler (DPI) for 12 weeks to patients with mild atopic asthma, who exhibited an early asthmatic response (EAR) and late asthmatic response (LAR) to a common inhaled allergen." (PMID 36140430, 2022). "The results of our study suggest that there might at least be local interplay between periostin and TSLP in airway inflammation in atopic asthma." (PMID 33203095, 2020). "The results of our study show that periostin and TSLP are associated with eosinophilic airway inflammation and seem to be important drivers of atopic asthma but not COPD pathobiology." (PMID 33203095, 2020). "We may speculate that similar link between periostin and TSLP action occurs in atopic asthma, where periostin produced by MCs can affect epithelial cells via integrin binding activation, resulting in TSLP secretion." (PMID 33203095, 2020).
Obesity (12 papers, 2019 to 2026). Accumulation of substantial excess body fat. "Obesity affects allergic airway inflammation through mast cell influx and the release of TSLP and IL-25." (PMID 36051916, 2022). "While IL-25 mainly protects from obesity by stimulating M2 macrophages and inducing lipolysis, TSLP acts trough activation of DCs to prime naïve T cells for differentiation into Th2 cells." (PMID 35844529, 2022). "Thus, there could be a critical role for Th2 cell induction through TSLP-activation promoting an unexpected link to skin barrier maintenance and sebum secretion during obesity." (PMID 35844529, 2022). "In recent years, also other alarmins, such as IL-25 and thymic stromal lymphopoietin (TSLP), have been investigated and, for both, a supporting role on the Th2 response and protective effect against obesity could be shown." (PMID 35844529, 2022).
atherosclerosis (11 papers, 2017 to 2023). A disease characterized by the build-up of fatty material and calcium deposition in the arterial wall resulting in partial or complete occlusion of the arterial lumen. "More importantly, we reported that LAP+ Tregs induced by nasal oxidized low-density lipoprotein or thymic stromal lymphopoietin attenuated atherosclerosis in apolipoprotein E-deficient (ApoE−/−) mice." (PMID 36405994, 2022). "Thymic stromal lymphopoietin (TSLP), a distant paralog of the cytokine IL-7, has been shown to be associated with atherosclerosis." (PMID 35321112, 2022). "A recent study demonstrated that apolipoprotein E-deficient (ApoE−/−) mice treated with TSLP developed significantly fewer atherosclerotic plaques in the aortic root compared with controls, along with decreased inflammation in the aorta, indicating a protective role of TSLP in atherosclerosis." (PMID 28615347, 2017). "In line with this study, our research detected that thymic stromal lymphopoietin–conditioned DCs ameliorate atherosclerosis development via inducing differentiation of Tregs." (PMID 36405994, 2022). "Some studies have proposed the role of TSLP in atherosclerosis, but in part the results are controversial." (PMID 35321112, 2022). "On the contrary, Yu and co‐workers reported an attenuation of atherosclerosis following TSLP administration in mice." (PMID 32285594, 2020). "In the present study, for the first time, we found that serum TSLP level was much lower in atherosclerosis patients." (PMID 28615347, 2017). "We found that serum level of TSLP was decreased in atherosclerosis patients and serum TSLP level positively correlated with HOTAIR expression in EC." (PMID 28615347, 2017). "Recent study demonstrated that thymic stromal lymphopoietin (TSLP) exerts a protective role in atherosclerosis." (PMID 28615347, 2017). "In contrast, Yu and co-workers reported that the expression of TSLP in the cardiovascular tissue of ApoE–/– mice was inhibited, and treatment with TSLP could prevent the development of atherosclerosis in these mice." (PMID 35321112, 2022). "The protective effect of TSLP on atherosclerosis may be related to the down-regulation of systemic inflammation." (PMID 35321112, 2022). "Recently, TSLP was reported to play a role in atherosclerosis." (PMID 35321112, 2022). "In this study, we investigated, whether TSLP is crucial for the reduction of atherosclerosis by Freund's adjuvant." (PMID 32285594, 2020). "TSLP‐TSLPR signalling is critical for CFA/IFA‐mediated attenuation of atherosclerosis." (PMID 32285594, 2020). "Under the stimulation of oxidized low-density lipoprotein (ox-LDL), human umbilical vein endothelial cells and vascular smooth muscle cells release large amounts of TSLP, which might activate DCs and then accelerate the development of atherosclerosis." (PMID 30123216, 2018). "In addition, we observed that serum TSLP level was much lower in atherosclerosis and there existed a positive correlation between TSLP and HOTAIR expression." (PMID 28615347, 2017). "TSLP has been shown to attenuate atherosclerosis in ApoE−/− mice." (PMID 28615347, 2017). "TSLP promoted proliferation and migration, and suppressed apoptosis in EC, indicating that TSLP may attenuate atherosclerosis through regulation of EC besides immunity regulation." (PMID 28615347, 2017). "Serum TSLP levels were much lower in atherosclerosis patients than in healthy donors." (PMID 28615347, 2017). "However, the expression level of TSLP in atherosclerosis patients, the effect of TSLP on EC and the exact molecular mechanism remains unknown." (PMID 28615347, 2017). "Taken together, TSLP-HOTAIR may be a potential therapy for EC dysfunction in atherosclerosis." (PMID 28615347, 2017). "Our results strongly indicated a close relationship between TSLP-HOTAIR pathway and atherosclerosis." (PMID 28615347, 2017). "However, the biological significance of TSLP in EC is still unknown in atherosclerosis." (PMID 28615347, 2017).
atherosclerosis (continued). "Moreover, in atherosclerosis patients, serum level of thymic stromal lymphopoietin was lower and positively correlated with HOTAIR expression in endothelial cells, suggesting a potential therapy for endothelial dysfunction in atherosclerosis." (PMID 32630452, 2020). "Moreover, serum levels of thymic stromal lymphopoietin (TSLP), belonging to IL-7 like cytokine family, decrease in atherosclerosis patients, and positively correlates with HOTAIR expression in endothelial cells." (PMID 31072041, 2019). "A positive correlation between serum TSLP level and HOTAIR expression of EC in atherosclerosis patients was observed (r2 =0.6702, P<0.0001), indicating that HOTAIR expression may be regulated by TSLP." (PMID 28615347, 2017). "In addition, we analyzed the correlation between serum TSLP level and HOTAIR expression of EC in atherosclerosis patients." (PMID 28615347, 2017). "Interestingly, however, TSLP expression is not affected by CpG, an adjuvant that does not alter the development of atherosclerosis." (PMID 32285594, 2020). "TSLP and HOTAIR may serve as a novel therapy for atherosclerosis." (PMID 28615347, 2017). "However, the functional role of HOTAIR in EC of atherosclerosis and whether HOTAIR is regulated by TSLP-induced activation of AKT pathway remains unclear." (PMID 28615347, 2017).